CLIC1 (CLIC family member 1)
Diseases named in the same sentence as CLIC1 in open-access papers (continued):
Sharing a sentence is not in itself a finding about the gene and the disease.
glioma (19 papers, 2012 to 2025). A benign or malignant brain and spinal cord tumor that arises from glial cells (astrocytes, oligodendrocytes, ependymal cells). "The present work demonstrated that elevated CLIC1 was linked with worse survival outcomes of gliomas." (PMID 38027011, 2023). "Our aim is to determine the therapeutic potential of targeting CLIC1 and to unveil the molecular mechanisms underlying its role in gliomas." (PMID 38027011, 2023). "According to these results, increased expression of CLIC1 was found to be associated with the histopathologic grading of the gliomas." (PMID 22578365, 2012). "Kaplan-Meier analysis using the log-rank test was performed to determine the association of CLIC1 expression with clinical outcome of glioma patients." (PMID 22578365, 2012). "The association of CLIC1 immunostaining with clinicopathological factors or prognosis of glioma patients was statistically analyzed." (PMID 22578365, 2012). "Moreover, both univariate and multivariate analysis shown that high CLIC1 expression was significantly associated with poor prognosis in patients with gliomas (P<0.001 and P=0.01, respectively)." (PMID 22578365, 2012). "Previous research has reported elevated CLIC1 levels in various neurological disorders and central nervous system cancers, such as Alzheimer’s disease and stroke." (PMID 40966238, 2025). "While, in agreement with our finding, 2AAA, a subunit of PP2A acting as a tumor-suppressor, is inactivated or dysregulated in about 60% of GBM patients, CLIC1 is overexpressed in several solid tumors including gliomas (reviewed)." (PMID 38607010, 2024). "The most highly connected gene in this module is CLIC1, a chloride ion channel with high expression and potential therapeutic and prognostic value in adult glioma." (PMID 38685127, 2024). "The expression of CLIC1 mRNA and protein is significantly elevated in high-grade gliomas and is enhanced with the increase in tumor WHO grade." (PMID 39707577, 2024). "The study integrated TCGA-GBM and TCGA-LGG samples and corrected batch effects for analyzing CLIC1 in glioma." (PMID 38027011, 2023). "In vitro experiments were conducted to measure apoptosis and cell mobility in U251 and U373 glioma cells following transfection of CLIC1 siRNAs." (PMID 38027011, 2023). "More importantly, suppressing CLIC1 notably induced glioma cell apoptosis and alleviated cell motility, proving that CLIC1 as a treatment vulnerability of glioma." (PMID 38027011, 2023). "CLIC1’s significance in cancer and glioma progression, as well as its impact on patient survival, present exciting avenues for future cancer research." (PMID 38027011, 2023). "Nevertheless, the formation and activation mechanisms of functional CLIC1 in glioma remains indistinct." (PMID 38027011, 2023). "Although CLIC1 is expressed ubiquitously in human tissues, CLIC1 was found to present aberrant overexpression in glioma versus normal tissues." (PMID 38027011, 2023). "Altogether, CLIC1 overexpression served as a prognostic factor of glioma patients and mediated malignant progression." (PMID 38027011, 2023). "CLIC-1 medicated glioma expansion via secreted extracellular vesicle communication has been recently considered a therapeutic target due to CLIC-1′s upregulation correlating with worse prognosis in GBM patients." (PMID 37241023, 2023). "The present work conducted a multi-omics analysis for investigating the significance of chloride intracellular channel 1 (CLIC1) in gliomas." (PMID 38027011, 2023). "The protein level of the CLIC1 in glioma cells transfected with si-CLIC1 and a control sequence were assessed by Western blotting." (PMID 38027011, 2023). "Research into CLIC1’s role in cancer and glioma progression and patient survival is promising, but further studies are needed to fully understand the mechanisms of action and develop targeted therapies." (PMID 38053842, 2023).
glioma (continued). "Our findings revealed that CLIC1 possessed the potential as a treatment vulnerability and actionable target in gliomas." (PMID 38027011, 2023). "In GBM, CLIC1 upregulation in the active tmCLIC1 conformation correlates with aggressiveness and, in low grade gliomas, with reduced patients’ survival." (PMID 35135603, 2022). "Isolated EVs from GSCs overexpressing CLIC1 increased tumor growth and engraftment when co-injected with a human glioma-derived cell line in an orthotopic xenograft model." (PMID 34298912, 2021). "One of these cargos is the chloride intracellular channel-1 (CLIC1), which is present in glioma stem cell (GSC)-derived EVs." (PMID 34298912, 2021). "Apart from EGFRvIII, EVs released by GBM cells (including GBM cell lines and GBM patient-derived glioma/cancer stem cell line (GSC/CSC)) were demonstrated to carry the chloride intracellular channel-1 (CLIC1) protein." (PMID 32707733, 2020). "Overall survival of glioma patients with high CLIC1 expression was significantly decreased than those with low CLIC1 expression in either Grades I~II subgroup (n=32; P=0.01) or Grades III~IV subgroup (n=96; P=0.008)." (PMID 22578365, 2012). "Further support for a possible role of CLIC1 in glioma pathogenesis derived from the analysis that revealed a strong correlation of CLIC1 expression with the histopathological staging and inversely, with the survival of the disease." (PMID 22578365, 2012). "Of the 128 patients with gliomas, the high expression of CLIC1 was detected in 69.5% (89/128) of patients." (PMID 22578365, 2012). "In the glioma sections, CLIC1 was mainly detected in the cytoplasm, which was consistent with previous studies on other cancers." (PMID 22578365, 2012). "In particular, the elevated CLIC1 expression also correlated with shorter overall survival in different glioma subgroups stratified according to the WHO grading." (PMID 22578365, 2012). "The aim of this study was to investigate the clinicopathological significance and prognostic value of CLIC1 expression in human gliomas." (PMID 22578365, 2012). "The over-expression of CLIC1 was detected in high-grade glioma tissues compared with those in low-grade tissues, and increased with ascending tumor WHO grades (P=0.005)." (PMID 22578365, 2012). "Suppressing CLIC1 resulted in apoptosis and attenuated cell motility of glioma cells." (PMID 38027011, 2023). "U251 and U373 glioma cells were transfected with si-CLIC1 to silence CLIC1 expression." (PMID 38027011, 2023). "Prognostic implication of CLIC1 was firstly investigated in glioma." (PMID 38027011, 2023). "Overall, CLIC1 was regarded as a therapeutic vulnerability of glioma." (PMID 38027011, 2023). "Increased expression of CLIC1 correlates to unfavorable prognostic outcomes of gliomas." (PMID 38027011, 2023). "This research seeks to contribute to a better understanding of the intricate relationship between chloride channels, specifically CLIC1, and glioma progression, which may open doors to new treatment strategies." (PMID 38027011, 2023). "The study then assessed the potential of CLIC1 as a therapeutic vulnerability of glioma." (PMID 38027011, 2023). "Furthermore, we evaluated the prognostic significance of CLIC1 protein expression levels in different subgroups of glioma patients stratified according to the WHO grading." (PMID 22578365, 2012). "However, the clinicopathological significance and prognostic value of CLIC1 in clinical glioma specimens are still unclear." (PMID 22578365, 2012). "Notably, high CLIC1 expression also significantly correlated with shorter overall survival time in different glioma subgroups." (PMID 22578365, 2012). "Our data provide the first evidence that CLIC1 expression might play an important role in the regulation of aggressiveness in human gliomas." (PMID 22578365, 2012). "In summary, our data provide the first evidence that CLIC1 expression might play an important role in the regulation of aggressiveness in human gliomas." (PMID 22578365, 2012).
glioma (continued). "Thus, CLIC1 not only facilitates glioma tumor growth but also affects the tumor microenvironment." (PMID 38027011, 2023). "The expression levels of CLIC1 mRNA were detected in 20 glioma and 10 non-neoplastic brain tissues normalized to GAPDH." (PMID 22578365, 2012). "We first detected high expression of CLIC1 in glioma tissues compared with non-neoplastic brain tissues." (PMID 22578365, 2012). "CLIC1 expression in human gliomas and nonneoplastic brain tissues was measured by real-time quantitative RT-PCR assay and immunohistochemistry." (PMID 22578365, 2012). "Additionally, there was also a significant difference in mRNA copies of CLIC1 between high-grade (III-IV) and low -grade (I-II) glioma tissue specimens (P=0.002)." (PMID 22578365, 2012). "In the present study, our data shown for the first time that the up-regulation of CLIC1 at both mRNA and protein levels in glioma tissues compared with its expression in non-neoplastic brain tissues." (PMID 22578365, 2012). "Additionally, the multivariate analysis identified CLIC1 expression (HR, 4.66; 95% CI, 2.31–10.29; P=0.01) and WHO grade (HR, 6.97; 95% CI, 2.12–12.46; P=0.008) as significant prognostic factors for glioma." (PMID 22578365, 2012). "The expression of CLIC1 protein was detected in 128 glioma specimens and 10 nonneoplastic brain tissues using immunohistochemical staining." (PMID 22578365, 2012). "The expression levels of CLIC1 mRNA were found to be distinctly increased in glioma tissues compared to non-neoplastic brain tissues, corresponding to the glioma WHO grades." (PMID 22578365, 2012). "Additionally, highly CLIC1 protein expression was significantly correlated with advanced WHO stage and low KPS scores, suggesting that this protein might be of clinical relevance in the aggressiveness of gliomas." (PMID 22578365, 2012). "The expression of CLIC1 at both mRNA and protein levels was significantly increased in high-grade (Grade III~IV) glioma tissues compared with that in low-grade (Grade I~II) and nonneoplastic brain tissues, and was up-regulated with ascending tumor World Health Organization (WHO) grades." (PMID 22578365, 2012). "While CLIC1 activity itself may not be a determinant in the development of GBM, its suppression appears to influence the characteristics of glioma stem cells and their response to novel biguanide derivatives." (PMID 38027011, 2023).
colon cancer (14 papers, 2007 to 2025). "Wang P’s study revealed that CLIC1 governs the movement and infiltration of colon cancer cells by modulating the ROS-mediated MAPK/ERK signaling pathway." (PMID 40948771, 2025). "Similar to its role in colon cancer, CLIC1 is involved in the migration and invasion of GC cells by regulating intracellular ROS production." (PMID 33856653, 2021). "The CI- channel (CLIC1) enhanced the invasion and migration of gastric and liver cancer cells 25-26, and K+/Ca2+ channels are frequently overexpressed in colon cancer 27-28." (PMID 33391422, 2021). "Among the identified proteins within this category, vimentin (VIME, three protein species) and chloride intracellular channel 1 (CLIC1) were significantly up-regulated in colon cancer tissues." (PMID 32353950, 2020). "Wang and colleagues first demonstrated that CLIC1 regulates the migration and invasion of colon cancer." (PMID 32812032, 2020). "We also examined the distribution of CLIC1 in T84 cells, a well-differentiated human colon cancer cell line." (PMID 17326840, 2007). "Distribution of CLIC1 was examined in Panc1 cells, a relatively undifferentiated, non-polarized human cell line derived from pancreatic cancer, and T84 cells, a human colon cancer cell line which can form a polarized epithelium that is capable of regulated chloride transport." (PMID 17326840, 2007). "Previous studies have also shown that hypoxia-reoxygenation (H-R) may increase intracellular ROS levels to activate the MAPK/ERK pathway and that the CLIC1 protein participates in the migration of LOVO colon cancer cells by regulating the ROS/ERK pathway during H-R." (PMID 33856653, 2021). "Besides, CLIC1 possibly regulates the intracellular ROS generation and promotes cancer cell proliferation and migration through ROS/ERK pathway in colon cancer." (PMID 27825122, 2016).
hepatocellular carcinoma (14 papers, 2009 to 2025). A malignant tumor that arises from hepatocytes. "Hepatocellular carcinoma (HCC) exhibits upregulated CLIC1 expression, associated with tumor invasiveness, metastasis, and poor prognosis." (PMID 38027011, 2023). "In hepatocellular carcinoma (HCC), upregulated CLIC1 is associated with aggressiveness, metastasis, and poor prognosis." (PMID 38053842, 2023). "The most studied protein, chloride intracellular channel 1 (CLIC1), is highly expressed in human hepatocellular carcinoma and is closely associated with tumor size, distant metastasis, pathological stage, and low survival rate." (PMID 39048663, 2024). "Another study also showed that CLIC1 is highly expressed in hepatocellular carcinoma, inhibits cell proliferation, and promotes the migration, invasiveness and apoptosis of hepatocellular carcinoma cells." (PMID 39048663, 2024). "In hepatocellular carcinoma, CLIC1 expression has been correlated with angiogenesis by regulating VEGF-A." (PMID 36826036, 2023). "CLIC1 has been reported as a potential biomarker and therapeutic target for some tumors such as oral squamous cell carcinoma, ovarian cancer, and hepatocellular carcinoma." (PMID 36826036, 2023). "Recent studies have found that CLIC1 is over-expressed in malignant tumors, such as hepatocellular carcinoma, gallbladder carcinoma, gastric carcinoma, and colorectal cancer." (PMID 22578365, 2012). "In hepatocellular carcinoma studies, CLIC1 overexpression increased cell viability." (PMID 40948771, 2025). "Studies have demonstrated that CLIC1 promotes hepatocellular carcinoma cell invasion." (PMID 39048663, 2024). "Next, a literature search was conducted to focus on proteins specifically associated with liver disease in general, which selected 20 proteins, seven of which (i.e., CEP55, CLIC1, EPS15L1, G6PD, KIF11, SLC1A5, and TK1) were found to be specifically associated with hepatocellular carcinoma." (PMID 37627157, 2023). "Using PalmGRET, we identified lung‐tropic proteins of EPs derived from lung metastatic hepatocellular carcinoma (HCC) in immunocompetent C3H mice, solute carrier organic anion transporter family member 2A1 (Slco2a1), alanine aminopeptidase (Anpep/Cd13), and chloride intracellular channel 1 (Clic1)." (PMID 33042758, 2020). "Even though a growing body of research has shown CLIC1 may have an oncogenic role in human hepatocellular carcinoma and medulloblastoma, the protein’s function in BC has not yet been examined." (PMID 36727059, 2022).
ovarian carcinoma (12 papers, 2015 to 2023). A malignant neoplasm originating from the surface ovarian epithelium. "Two of the known ovarian cancer-related genes are also associated with ovarian cancer prognostic outcomes (CLIC1 and NQO1)." (PMID 34215221, 2021). "In ovarian cancer, CLIC1 has been identified as a promising biomarker with prognostic value, impacting patient survival and possibly serving in conjunction with CLIC4." (PMID 38027011, 2023). "Knockdown of either CLIC4 or CLIC1 resulted in slower growth of ovarian cancer cells suggesting a role of CLICs in cell proliferation and cell migration." (PMID 35223789, 2022). "Its role in carcinogenesis was demonstrated to be correlated with the activity of CLIC1 as glutathione-dependent oxidoreductase activity that drive angiogenesis and increases invasiveness of cancer cells with transglutaminase-2 in ovarian cancer." (PMID 34357102, 2021). "CLIC1 is shown to regulate the redox-sensitivity of ovarian cancer cells and is predicted to be a potential marker for lymphoblastic leukemia." (PMID 32116799, 2020). "Along with CLIC4, CLIC1 is a promising biomarker for epithelial ovarian cancer where its expression predicts patient survival." (PMID 32116799, 2020). "In ovarian cancer, expression of CLIC1 was shown to be directly related to patient survival outcome." (PMID 32116799, 2020). "Levels of both proteins were significantly elevated in sera from ovarian cancer patients compared with normal and benign controls, with receiver operating characteristic curves having an area under the curve of 0.79 for CLIC1 and 0.86 for CLIC425,27." (PMID 30282979, 2018). "A quantitative proteomics was performed with A2780-CLIC1 KD cells and A2780-NCi cells to explore the mechanism of CLIC1 during tumorigenesis of ovarian cancer." (PMID 27825122, 2016). "Based on this study, CLIC1 is expected to be a potential biomarker and therapeutic target in ovarian cancer." (PMID 27825122, 2016). "High levels of CLIC1 in ovarian cancer tumor cell cytoplasm and membrane were observed, as well as high levels of LGALS3BP in tumor cell membrane." (PMID 27825122, 2016). "The ovarian cancer cell line A2780 with CLIC1 knock-down showed slower proliferation in vitro and in vivo." (PMID 27825122, 2016). "To determine the function of CLIC1 on progression of ovarian cancer, we established A2780 CLIC1 KD cell line by knocking-down the expression of CLIC1 in ovarian cell line A2780." (PMID 27825122, 2016). "We found that both of CTPS1 and CLIC1 are up regulated in ovarian cancer, while down regulated in CLIC1 KD cells." (PMID 27825122, 2016). "Some proteins located in the cell membrane or secreted out of cell were up regulated in ovarian cancer, such as CLIC1 and LGALS3BP." (PMID 27825122, 2016). "The positive expression of CLIC1 was 92.3% and 30.8% in ovarian cancer tissues and normal ovary tissues, respectively (p<0.001)." (PMID 27825122, 2016). "From these results, we concluded that CLIC1 promoted tumorgenesis and progression, which is a potential therapeutic target for epithelial ovarian cancer." (PMID 27825122, 2016). "Of further interest, CLIC1 protein was recently found circulating in human serum or plasma, and proposed as a potential biomarker in nasopharyngeal and ovarian carcinoma." (PMID 26429879, 2015). "CLIC1 is a biomarker for ovarian cancers holding prognostic value." (PMID 32116799, 2020). "Taken together, LGALS3BP and CLIC1 were up regulated in ovarian cancer patients." (PMID 27825122, 2016). "Besides, CLIC1-knockdown cells showed an increased sensitivity to hydrogen peroxide and cisplatin, suggesting that CLIC1 was involved in regulation of redox and drug resistance in ovarian cancer cells." (PMID 27825122, 2016). "The results revealed a statistically significant high level of these two proteins in ovarian cancer tissues compared with normal control (p<0.005 and p<0.001), indicating CLIC1 or LGALS3BP may accelerate the development of tumor." (PMID 27825122, 2016).